VDAC1 (voltage dependent anion channel 1)
Diseases named in the same sentence as VDAC1 in open-access papers (continued):
Sharing a sentence is not in itself a finding about the gene and the disease.
Stroke (2 papers, 2015 to 2018). Sudden impairment of blood flow to a part of the brain due to occlusion or rupture of an artery to the brain. "Overexpression of VDAC1 has also been found in Parkinson’s disease, indicating that different pathogenesis involves in neurodegenerative diseases and stroke." (PMID 30305621, 2018). "Therefore, the inhibition of the activity of MCU or disruption of VDAC1-MCU interaction might be a strategy to stroke and degenerative diseases." (PMID 25753332, 2015).
acromegaly (1 paper, 2024). Acromegaly is an acquired disorder related to excessive production of growth hormone (GH) and characterized by progressive somatic disfigurement (mainly involving the face and extremities) and systemic manifestations. "A significant down-regulation of VDAC1 gene expression was observed in the acromegaly (median RQ = 0.47; P = 0.029) and NF groups (median RQ = 0.57; P = 0.002) compared to the normal pituitary tissue." (PMID 39449743, 2024). "Compared to normal tissue, there was a significant reduction in VDAC1 expression in the Acromegaly (p=0.029) and NF (p=0.002) groups." (PMID 39449743, 2024). "In this study, we found lower VDAC1 expression in acromegaly and NF adenomas than in normal pituitary tissue." (PMID 39449743, 2024).
acute myeloid leukemia (1 paper, 2023). Acute myeloid leukemia (AML) is a group of neoplasms arising from precursor cells committed to the myeloid cell-line differentiation. "In light of the expression data of the VDAC1 gene and its pseudogene VDAC1P8 retrieved from public repository, we decided to experimentally evaluate their expression in 5 different acute myeloid leukemia cell lines." (PMID 37344914, 2023).
asthma (1 paper, 2020). "As expected, VDAC1 was highly expressed in A. fumigatus‐induced asthma, and its expression was controlled by treatment with IC87114 or 4‐PBA." (PMID 31713846, 2020).
brain injury (1 paper, 2025). Acute and chronic (see also brain INJURIES, CHRONIC) injuries to the brain, including the cerebral hemispheres, CEREBELLUM, and brain STEM. "Brain injury promotes Ca2+ influx and mitochondrial Ca2+ loading via voltage-dependent anion channel 1 (VDAC1) and the mitochondrial Ca2+ uniporter (MCU), leading to mitochondrial dysfunction and cytochrome c-mediated apoptosis." (PMID 41284727, 2025).
brain tumors (1 paper, 2016). "This group also included proteins associated with metabolism and apoptosis, included proteins that were reported in other cancers, including liver and brain tumors, but not CLL, such as VDAC1, VDAC2, AIF and other mitochondrial proteins associated with metabolism and apoptosis regulation (group B)." (PMID 27078856, 2016).
cervical adenocarcinoma (1 paper, 2022). An adenocarcinoma arising from the cervical epithelium. "The treatment of pro-apoptosis inducer, hydrogen peroxide on Hela (human cervical adenocarcinoma) cells resulted in increased cytosolic Ca2+ and overexpressed oligomerised VDAC1 mediating the release of cytochrome c and apoptosis." (PMID 35258800, 2022).
clear cell carcinoma (1 paper, 2022). "We found that VDAC1 was highly expressed in the serous and clear cell carcinoma cell lines and in the simvastatin-responsive cell lines 4C and 7C, whereas it was expressed at low levels in the mucinous carcinoma cell lines and in the simvastatin-refractory cell lines 2C and 8C." (PMID 35215239, 2022).
dilatation (1 paper, 2020). "Our findings support the notion that both MI and chronic heart disease associated with LV dilatation markedly increase VDAC1 expression levels in the LV myocardium." (PMID 33328613, 2020).
Duchenne muscular dystrophy (1 paper, 2022). Duchenne muscular dystrophy (DMD) is a neuromuscular disease characterized by rapidly progressive muscle weakness and wasting due to degeneration of skeletal, smooth and cardiac muscle. "In a recent study, the number of MERCS calculated as the proximity between IP3R1 and VDAC1 was upregulated in Duchenne muscular dystrophy (DMD) cardiomyocytes." (PMID 36092728, 2022).
epithelial dysplasia (1 paper, 2023). "Materials and methods: 103 biopsies including 49 oral squamous cell carcinoma, 33 epithelial dysplasia, and 21 fibrous hyperplasia samples were immunohistochemically stained with anti-VDAC1 antibodies for semi-quantitative evaluation." (PMID 37046443, 2023).
esophageal cancer (1 paper, 2023). A primary or metastatic malignant neoplasm involving the esophagus. "Specifically for esophageal carcinoma, the gene expression profiles from patients with a family history of esophageal cancer were analyzed by cDNA microarray and VDAC1 was one of the calcium signaling pathways genes that were found to be down-regulated." (PMID 37046443, 2023). "Within this list, the position of esophageal carcinoma is somewhat unclear because VDAC1 was found to be down-regulated in human esophageal carcinoma." (PMID 37046443, 2023).
glaucoma (1 paper, 2024). Increased pressure in the eyeball due to obstruction of the outflow of aqueous humor. "The function of VDAC1 and its oligomerized form was also studied in a model of glaucoma that inflicted mechanical trauma to the eye." (PMID 38927058, 2024). "Nonetheless, the involvement of VDAC1 oligomerization in glaucoma can be deduced from an experiment using VBIT12, a specific inhibitor of VDAC1 oligomerization." (PMID 38927058, 2024).
gout (1 paper, 2021). A condition characterized by painful swelling of the joints, which is caused by deposition of urate crystals. "The final nine surviving monocyte-specific differentially methylated CpG sites were mapped to eight genes (PRKCZ, CIDEC, VDAC1, CPT1A, BIRC2, BRCA1, STK11, and NLRP12) that have not previously been studied in the field of gout genetics." (PMID 33493135, 2021).
HCMV infection (1 paper, 2016). "ATP5A a nuclearly encoded subunit of respiratory complex V, and the mitochondrial outer membrane protein porin (VDAC1) were not upregulated by HCMV infection of U373 cells, consistent with our SILAC data." (PMID 27025248, 2016).
hearing loss (1 paper, 2025). "A better understanding of the involvement of VDAC1 in hearing loss could lead to the development of new therapeutic strategies." (PMID 40285415, 2025).
hyperaldosteronism (1 paper, 2020). Overproduction of aldosterone by the adrenal glands, which may lead to hypokalemia and/or hypernatremia. "Our ventricular findings in patients with chronic heart disease, as well as in rats with hyperaldosteronism, are in line with the documentation of marked VDAC1 overexpression in rats subjected to hypertrophy by renal artery ligation." (PMID 33328613, 2020). "To substantiate the noted VDAC1 overexpression in human cardiac pathologies, we next evaluated VDAC1 expression levels in rat cardiac tissue samples from our recent study on MI and hyperaldosteronism as triggering factors for AF39." (PMID 33328613, 2020). "The findings in rats further support this idea and indicate that both MI and hyperaldosteronism can increase VDAC1 levels not only in the ventricular tissue, but also in the atria." (PMID 33328613, 2020). "Thus, we decided to test in further detail the possible roles of VDAC1 in the setting of hyperaldosteronism, with a specific focus on the atria." (PMID 33328613, 2020). "The fact that hyperaldosteronism per se could trigger a global increase of VDAC1 in the heart focuses specific attention to the possible role of aldosterone as the main trigger for VDAC1 overexpression in heart disease." (PMID 33328613, 2020). "Finally, the study demonstrated that treatment with the VDAC1 oligomerization apoptosis and mitochondria dysfunction inhibitor, VBIT-4, reduces atrial fibrosis in the setting of hyperaldosteronism." (PMID 33328613, 2020).
Hypercholesterolemia (1 paper, 2022). An increased concentration of cholesterol in the blood. "Hypercholesterolemia and pravastatin changed the interaction pattern between Ip3r1 and Vdac1 in macrophages." (PMID 35372506, 2022).
Hypertension (1 paper, 2025). The presence of chronic increased pressure in the systemic arterial system. "MERCs regulate calcium transfer via voltage-dependent anion channel 1 (VDAC1) and inositol 1,4,5-trisphosphate receptor (IP3R), mediated by glucose-regulated protein 75 (GRP75).85,86 Aging disrupts this complex, leading to mitochondrial calcium overload and hypertension." (PMID 41551943, 2025).
kidney cancer (1 paper, 2020). Primary or metastatic malignant neoplasm involving the kidney. "Our study describes, for the first time, a VDAC1-ΔC-dependent mechanism in which kidney cancer cells can maintain glycolysis in the presence of the EMT signature, which promotes survival of cells surrounded by an unfavorable microenvironment." (PMID 32194829, 2020).
liver diseases (1 paper, 2024). "Future research should focus on validating these findings in human studies and exploring the broader implications of Pgam5 and VDAC1 modulation in liver diseases." (PMID 38464835, 2024).
lung injury (1 paper, 2024). "Oliver directly binds to mitochondrial protein VDAC1 at Y022 and K028, prevents VDAC1 oligomerization to block Ox‐mtDNA release into the cytoplasm, further inhibits NLRP3 inflammasome activation in macrophages, finally alleviates lung inflammation and acute lung injury in mice." (PMID 39556713, 2024).
lymphopenia (1 paper, 2021). Reduction in the number of lymphocytes. "Interestingly, the presence of H3K27me3+VDAC1+ T cells was highly predictive of the development of lymphopenia during the course of hospitalization." (PMID 33691089, 2021).
malignant mesothelioma (1 paper, 2022). A malignant neoplasm of the pleura or peritoneum, arising from mesothelial cells. "Expression levels of VDAC1 in samples from healthy individuals and patients with malignant mesothelioma were assessed in a tissue microarray slide by immunohistochemistry (IHC) using VDAC1-specific antibodies." (PMID 35883451, 2022).
obstructive jaundice (1 paper, 2025). A finding indicating increased bilirubin levels in the blood and urine, due to intrahepatic or extrahepatic obstruction of the biliary system. "Therefore, VDAC1 has the potential to be an effective target for alleviating liver injury caused by obstructive jaundice." (PMID 39877630, 2025). "To further investigate the potential relationship between VDAC1 and cell apoptosis in liver injury induced by obstructive jaundice, we first employed IHC to assess the expression of VDAC1 protein in the liver tissues." (PMID 39877630, 2025). "Exploring the role of VDAC1 in hepatocyte apoptosis during acute liver injury induced by obstructive jaundice." (PMID 39877630, 2025). "A cell model of obstructive jaundice was established to investigate the direct correlation between VDAC1 and hepatocyte apoptosis." (PMID 39877630, 2025). "Hence, the VDAC1 protein holds significant clinical implications for investigating the mechanism of liver cell damage induced by obstructive jaundice." (PMID 39877630, 2025).
oral epithelial dysplasia (1 paper, 2023). "The study’s main strength is the first-time demonstration of VDAC1 expression in cases of various oral cavity lesions, such as oral squamous cell carcinoma, oral epithelial dysplasia, and fibrous hyperplasia, which represented malignant, premalignant, and malignancy-neutral oral lesions." (PMID 37046443, 2023).
osteoporosis (1 paper, 2015). A condition of reduced bone mass, with decreased cortical thickness and a decrease in the number and size of the trabeculae of cancellous bone (but normal chemical composition), resulting in increased fracture incidence. "Above all, our findings suggested a novel mechanism for osteoporosis, which is attenuation of monocyte apoptosis, as supported by the 4 apoptosis genes’ (DAXX, PLK3, VDAC1 and PDCD5) down-regulation in the low BMD subjects." (PMID 25659073, 2015).
ovarian clear cell cancer (1 paper, 2022). An invasive malignant neoplasm that arises from the ovary and is characterized by a predominance of clear and hobnail malignant epithelial cells. "In addition, VDAC1 regulates metabolites, ions, and reactive oxygen species, which are highly associated with ovarian clear cell carcinoma." (PMID 35215239, 2022). "Although further studies are needed to determine how statins regulate VDAC1, the effectiveness of statins against ovarian clear cell carcinoma is promising." (PMID 35215239, 2022).
paraganglioma (1 paper, 2022). A benign or malignant neoplasm arising from paraganglia located along the sympathetic or parasympathetic nerves. "In most algorithms, a positive correlation between VDAC1 expression and regulatory T-cell immune infiltration could be observed in pheochromocytoma and paraganglioma (PCPG)." (PMID 35958281, 2022).
periodontitis (1 paper, 2026). An acute or chronic inflammatory process that affects the tissues that surround and support the teeth. "The mitochondrial Ca2+ channel proteins, voltage dependent anion channel 1 (VDAC1) and mitochondrial calcium uniporter (MCU), were significantly upregulated in periodontitis gingiva, and their expression positively correlated with probing depth." (PMID 42196298, 2026).
pituitary adenoma (1 paper, 2024). "Differential expression of VDAC1, VDAC2, BAX and BAK genes according to pituitary adenoma size and invasiveness." (PMID 39449743, 2024).
preeclampsia (1 paper, 2017). Preeclampsia is a hypertensive disorder of pregnancy that is characterized by new-onset hypertension with proteinuria presenting after 20 weeks of gestation, and depending on mild or severe forms may initially present with severe headache, visual disturbances, and hyperreflexia. "In late-onset preeclampsia, expression levels of essential mitochondria-related proteins VDAC1, TFAM, hexokinase 1, PGC-1α and PGC-1β, and autophagy marker LC3A, were significantly elevated." (PMID 28736722, 2017).
progeria (1 paper, 2024). "In general, our current results revealed a novel mechanism for senescence-associated phenotypes of postmitotic myofiber in progeria-aged mice, which involves increased cGAS-Sting activation caused by mitochondria damage, VDAC1 oligomerization, and mtDNA release." (PMID 39039044, 2024). "In our study, VBIT4 treatment of Z24−/− myofibers in vitro was effective in inhibiting mtDNA-induced cGAS-Sting activation and expression of SASP factors, suggesting that VDAC1 can be a novel molecular target for improving progeria aging-associated defective phenotypes." (PMID 39039044, 2024). "Therefore, we propose that progeria-aged myofibers may develop increased VDAC1 oligomerization, which leads to increased mtDNA release into cytosol and innate immune activation." (PMID 39039044, 2024).
retinal degeneration (1 paper, 2022). Degeneration of the retina. "Our results revealed that the retinal degeneration triggered by VDAC1 knockdown could be related to oxidative stress followed by caspase-independent apoptosis." (PMID 35449127, 2022). "We next aimed to examine the role of VDAC1 in retinal degeneration by inhibiting its activity." (PMID 35449127, 2022).
retinal detachment (1 paper, 2022). An eye emergency condition which may lead to blindness if left untreated. "VDAC1 knockdown induced inward folds of the ONL associated with local retinal detachments and thinning of the INL." (PMID 35449127, 2022).
schizophrenia (1 paper, 2017). A major psychotic disorder characterized by abnormalities in the perception or expression of reality. "Additionally, Ingenuity Global Functional Analysis revealed significant enrichment of the identified protein dataset for proteins previously shown to be linked to schizophrenia, including GAP43, VDAC1 and SNCB, all of which have been shown to play a role in synaptic communication." (PMID 28570644, 2017).
serous cystadenocarcinoma (1 paper, 2022). A malignant serous cystic neoplasm usually involving the ovary or the pancreas. "Similarly, GRP75 and VDAC1 were remarkably high-expressed in OC tissues, especially in serous cystadenocarcinoma tissues." (PMID 35541901, 2022).
tauopathy (1 paper, 2020). Neurodegenerative disorders involving deposition of abnormal tau protein isoforms (tau proteins) in neurons and glial cells in the brain. "Thus, the expression of mitochondrial proteins ANT1 and VDAC1 in Tg mice CA1 neurons are differently affected by age and the status of tauopathy." (PMID 32131898, 2020).
thyroid tumour (1 paper, 2016). "Recently, a systematic analysis demonstrated that VDAC-1 is up regulated in breast, colon, liver, lung, pancreatic, and thyroid tumour tissues." (PMID 27936075, 2016).
thyroide (1 paper, 2016). "VDAC1 was found to be over-expressed in several types of cancers, such as lung, cervical, thyroide and ovarey cancer, yet this report is the first to demonstrate VDAC1 over-expression in CLL." (PMID 27078856, 2016).
vitiligo (1 paper, 2026). Generalized well circumscribed patches of leukoderma that are generally distributed over symmetric body locations and is due to autoimmune destruction of melanocytes. "Importantly, genetic silencing or pharmacological inhibition of VDAC1 with VBIT-4 effectively blocked mtDNA release, suppressed downstream inflammatory cascades, and alleviated depigmentation and CD8+ T cell infiltration in a murine vitiligo model." (PMID 41851094, 2026).